ALK (ALK receptor tyrosine kinase)
Diseases named in the same sentence as ALK in open-access papers (continued):
Sharing a sentence is not in itself a finding about the gene and the disease.
thymoma (3 papers, 2017 to 2022). A neoplasm arising from the epithelial cells of the thymus. "Type A and B3 thymoma and thymic carcinoma tissues were stained with antibodies to ALK, HER2, HER3, MET, phospho-mTOR, PDGFRA, PDGFRB, PD-L1, p16INK4A, PTEN and ROS1 to identify potential targets for therapy." (PMID 27844328, 2017). "Significant enrichment of mutated genes of the RAS and PI3K-Akt signalling pathways was reported in thymomas (AKT3, ALK, CSF1R, FGFR4, KRAS, NRAS, HRAS, PIK3CA), and their role in thymoma development was suggested." (PMID 35884448, 2022). "Immunohistochemistry was performed to study the expression of ALK, HER2, HER3, MET, phospho-mTOR, p16INK4A, PDGFRA, PDGFRB, PD-L1, PTEN and ROS1 in type A and B3 thymomas and thymic carcinomas." (PMID 27844328, 2017). "None of the thymomas and thymic carcinomas analyzed expressed ALK, HER2 and HER3." (PMID 27844328, 2017).
thyroid nodule (3 papers, 2022 to 2025). A small circumscribed mass in the THYROID GLAND that can be of neoplastic growth or non-neoplastic abnormality. "Analysis of more than 100,000 FNA samples, including both benign and malignant thyroid nodules, identified 895 instances of NTRK, RET, ALK and BRAF fusions, representing potentially actionable kinase fusions." (PMID 36675685, 2022).
type 2 diabetes mellitus (3 papers, 2021 to 2025). A type of diabetes mellitus that is characterized by insulin resistance or desensitization and increased blood glucose levels. "miR-1271 caused the downregulation of both ALK and RYK, which were found to be in charge of the cytoskeleton structural degeneration in both AD and Type 2 diabetes mice." (PMID 38605867, 2024). "Anaplastic lymphoma kinase (ALK) and Receptor-Like Tyrosine Kinase (RYK), two non-canonical receptor tyrosine kinases (RTKs), have been shown to target miR-1271 in post-mortem AD and Type 2 diabetes tissues." (PMID 38605867, 2024).
Uterine leiomyoma (3 papers, 2018 to 2026). The presence of a leiomyoma of the uterus. "ALK is negative in normal uterine tissues, and to date, no ALK rearrangements have been detected in uterine leiomyomas." (PMID 41560086, 2026). "It is worth mentioning that no ALK fusion genes have been detected in uterine leiomyomas thus far." (PMID 39372869, 2024).
acral lentiginous melanoma (2 papers, 2017 to 2019). A form of melanoma occurring most often on the plantar, palmar, subungual, and periungual skin. "While the sample size was small, the authors suggested that ALK translocations in acral melanomas may be associated with a poorer prognosis." (PMID 28895885, 2017). "ALK translocations were identified by fluorescent in situ hybridization in 4 out of 30 primary acral melanomas." (PMID 28895885, 2017). "One patient with heavily pretreated acral lentiginous melanoma carrying a ROS1-GOPC fusion was treated with entrectinib (TKI with activity against tropomyosin receptor kinase (Trk), ROS1 and ALK), leading to a PR with 38% reduction in tumor burden at 3 months and 55% at 11 months." (PMID 30719217, 2019).
acute appendicitis (2 papers, 2016 to 2024). "The second case is a previously healthy 58-year-old man with advanced ALK-positive NSCLC who was started on first-line treatment with alectinib and subsequently diagnosed with asymptomatic acute appendicitis on re-staging CT abdomen." (PMID 39391245, 2024).
adenoid cystic carcinoma (2 papers, 2023 to 2025). A malignant tumor arising from the epithelial cells. "Interestingly, in a study, AuNPs were coated with Crizotinib, an anaplastic lymphoma kinase (ALK) inhibitor, for targeting and radiosensitization of adenoid cystic carcinomas (ACC)." (PMID 37046740, 2023).
alcohol use disorder (2 papers, 2011 to 2017). "Finally, sequencing of human ALK led to the discovery of four polymorphisms associated with a low level of response to ethanol, an intermediate phenotype that is predictive of future alcohol use disorders (AUDs)." (PMID 21799923, 2011). "Thus, manipulation of ALK signaling may represent a novel approach to treating alcohol use disorder (AUD)." (PMID 28860990, 2017).
atrial fibrillation (2 papers, 2020 to 2021). A disorder characterized by an electrocardiographic finding of a supraventricular arrhythmia characterized by the replacement of consistent P waves by rapid oscillations or fibrillatory waves that vary in size, shape and timing and are accompanied by an irregular ventricular response. "A 76 year old ‘never smoker’ female with an ALK-rearranged left upper lobe T2 N0 NSCLC experienced a stroke following elective DC cardioversion for new atrial fibrillation." (PMID 32762670, 2020).
B-cell neoplasm (2 papers, 2025). A group of heterogeneous lymphoid tumors generally expressing one or more B-cell antigens or representing malignant transformations of B-lymphocytes. "In contrast, ALK+ LBCL is a distinct entity classified under B-cell neoplasms, which often results from chromosomal aberrations involving the ALK gene, leading to aberrant expression of the ALK protein." (PMID 40428800, 2025).
bladder (2 papers, 2016 to 2026). "Histopathological examination confirmed IMT of the urinary bladder (IMTUB) with positive immunohistochemical staining for ALK, vimentin, and actin." (PMID 41827463, 2026).
breast tumors (2 papers, 2013 to 2020). "In contrast to studies identifying genetic abnormalities of ALK in other tumor types, results of investigations evaluating breast tumors for ALK genetic abnormalities have been inconsistent." (PMID 24102046, 2013). "Analysis of breast tumors in the TGCA database revealed a significant association between basal-like breast tumors that have characteristics of IBC breast tumors and gains in ALK copy number." (PMID 24102046, 2013). "The generality of gains in ALK copy number in basal-like breast tumors with IBC characteristics was demonstrated by analysis of 479 breast tumors using the TGCA data-base and our newly developed 79 IBC-like gene signature." (PMID 24102046, 2013).
Castleman disease (2 papers, 2012). Castleman disease (CD) is a benign lymphoproliferative disorder that may present as a localized or multicentric form. "Therefore, future studies should aim on the copy number alterations in newly defined uncommon large B-cell lymphoma entities, such as EBV + DLBCL of the elderly, ALK positive DLBCL and LBCL arising in HHV8-associated multicentric castleman disease." (PMID 22967872, 2012).
choroid plexus carcinoma (2 papers, 2019 to 2023). A malignant neoplasm arising from the choroid plexus. "The HBL tumor of this study exhibited exon 25 and exon 9 mutations in ALK and FGFR3 genes; however, mutations in exon 29 and exon 16 in these two genes were previously reported in an atypical-choroid plexus papilloma (a-CPP) tumor." (PMID 37273678, 2023). "All analyzed 19 anaplastic ependymomas, 4 choroid plexus carcinomas and 2 atypical teratoid rhabdoid tumors were immunonegative for ALK expression." (PMID 30523493, 2019).
chronic periodontitis (2 papers, 2013 to 2021). A chronic inflammatory process that affects the tissues that surround and support the teeth. "We presented an unusual case of ALK-negative ALCL on the gingiva associated with advanced chronic periodontitis that mimicked some clinical features of a hyperplastic gingival benignancy, which manifested in a 57-year-old HIV-seropositive man." (PMID 23840974, 2013).
clear cell sarcoma (2 papers, 2020 to 2023). A rare malignant neoplasm with melanocytic differentiation characterized by the presence of polygonal or spindle shaped clear cells. "On the other hand, crizotinib, an ALK inhibitor which has been investigated to rhabodmyosarcoma with ALK expression above, is known as inhibiting other targets such as MET, and showed some clinical responses to clear cell sarcomas overexpressing MET." (PMID 31963219, 2020).
CNS lymphoma (2 papers, 2024 to 2025). "ALK-positive ALCL is a rare primary CNS lymphoma with limited reported cases." (PMID 40699359, 2025). "Non-CNS lymphomas with ALK expression generally have better prognosis in comparison to their ALK-negative counterparts, as they tend to respond well to chemotherapy and to remain in remission." (PMID 38339401, 2024). "Interestingly, although ALK-inhibition therapy with second- and third-generation drugs has shown some potential in ALK-positive, non-CNS lymphomas, none of the identified patients received ALK-inhibition therapy." (PMID 38339401, 2024).
duodenal carcinoma (2 papers, 2023 to 2025). "The sole case previously reported demonstrated the efficacy of an ALK inhibitor in a patient with duodenal carcinoma harboring ALK fusion." (PMID 40160872, 2025). "And this time, we experienced a case of ALK fusion duodenal carcinoma that developed resistant after initially responding to alectinib." (PMID 40160872, 2025). "We previously reported the first case of a patient with ALK fusion-positive duodenal carcinoma that responded to alectinib." (PMID 40160872, 2025). "While the efficacy of drugs such as lorlatinib has been documented in ALK-positive NSCLC following progression on second-generation ALK inhibitors, this represents the first such case in duodenal carcinoma." (PMID 40160872, 2025). "This is the first report demonstrating the efficacy of brigatinib after alectinib failure in a patient with duodenal carcinoma harboring ALK fusion." (PMID 40160872, 2025). "In conclusion, to our knowledge, this is the first reported case of a response to brigatinib treatment following alectinib failure in a patient with ALK fusion-positive duodenal carcinoma." (PMID 40160872, 2025). "We present a patient with ALK fusion-positive duodenal carcinoma treated with brigatinib following alectinib failure." (PMID 40160872, 2025). "We report the case of a 64-year-old woman who was diagnosed with anaplastic lymphocyte kinase (ALK) fusion-positive advanced duodenal carcinoma." (PMID 36713517, 2023). "This is the first report of the efficacy of alectinib in a patient with duodenal carcinoma harboring ALK fusion." (PMID 36713517, 2023).
ependymoma (2 papers, 2019 to 2025). A WHO grade II, slow growing tumor of children and young adults, usually located intraventricularly. "Nonetheless, the role of protein kinase signaling has been implied in ependymoma tumorigenesis, prompting several ongoing studies evaluating TKIs targeting RET, ALK, ROS, IGFR, PDGFR, FGFR, or EGFR, as well as inhibitors targeting PI3K, mTOR, KIT, and CDK4." (PMID 40238025, 2025). "All 19 anaplastic ependymomas, 4 CPC and 2 AT/RT were negative for ALK expression." (PMID 30523493, 2019).
gastric tumors (2 papers, 2022 to 2025). "A few studies have described other ALK molecular alterations in gastric tumors which do not include gene overexpression." (PMID 36145589, 2022).
gastrointestinal lymphoma (2 papers, 2025). A non-Hodgkin or Hodgkin lymphoma that arises from any part of the digestive system, with the bulk of the disease localized to that site. "During the same period, 2,568 gastrointestinal lymphomas were diagnosed, with ALK+ ALCL representing 0.19% of these cases." (PMID 41584605, 2025).
glioneuronal tumor (2 papers, 2020 to 2023). "More recently, a novel MC of glioneuronal tumor (called the “glioneuronal tumor, not otherwise specified, subtype A") harboring RTK (ALK, NTRK1, NTRK2, NTRK3, and MET) fusions and MAPK (RAF1) fusions have been isolated by DNA‐methylation profiling." (PMID 37349135, 2023).
Hepatic fibrosis (2 papers, 2024). The presence of excessive fibrous connective tissue in the liver. "Consistently, we noted specific upregulation of genes enriched in ALK signaling in aged Myof (CLTC, RPS6, STAT3, etc.), which is studied extensively in liver fibrosis." (PMID 37378670, 2024).
histiocytic lymphoma (2 papers, 2017 to 2021). "For instance, removal of lipoproteins from media used to culture ALK+ anaplastic large T cell lymphoma (ALK+ ALCL) cell lines (SR-786, SUDHL1) and a histiocytic lymphoma cell line (U937) induced ferroptosis." (PMID 33208460, 2021). "Recently, a number of cell lines were found to be auxotrophic for cholesterol, including the cell lines SR-786 (ALK+ ALCL), SUDHL1 (ALK+ ALCL), and U937 (isolated from histiocytic lymphoma, but of myeloid lineage), among others." (PMID 33208460, 2021). "First, studies performed on crizotinib upon its discovery showed that a high concentration of crizotinib (defined as >300 nM) displayed off-target effects; and the IC50 for U937, a histiocytic lymphoma cell line used as a negative control (as it expresses neither ALK nor c-Met) was 257 nM." (PMID 29143801, 2017).
histiocytoma (2 papers, 2022 to 2025). A mesenchymal tumor composed of fibroblastic and histiocytic cells. "This fusion confirmed the diagnosis of EFH, a distinctive variant of fibrous histiocytoma associated with ALK rearrangement." (PMID 40688914, 2025).
Hyperglycemia (2 papers, 2024 to 2025). An increased concentration of glucose in the blood. "The exact mechanism of lorlatinib causing hyperglycemia is currently unclear; however, it is known that the ALK gene is part of the insulin receptor protein-tyrosine kinase receptor super family and can structurally mimic insulin receptors." (PMID 41322009, 2025). "Lorlatinib is an effective treatment for ALK-positive NSCLC, but it is associated with potential adverse metabolic effects, including hyperglycemia, insulin resistance, and DKA in rare cases." (PMID 41322009, 2025). "For SAF-189s, the incidence rate of hyperglycemia was relatively high (55.74%) compared with other ALK inhibitors." (PMID 39081957, 2024). "It is speculated that inhibiting the ALK gene can lead to decreased insulin secretion, leading to hyperglycemia." (PMID 41322009, 2025).
hypogonadotropic hypogonadism (2 papers, 2015 to 2020). Abnormal ovarian or testicular function due to insufficient hormonal stimulation from the hypothalamic-pituitary axis. "In this study of ALK of loss of function mice we present data supporting a role for ALK in hypogonadotropic hypogonadism in male mice." (PMID 25955180, 2015). "In mammalian systems, ALK drives neurite outgrowth and promotes neuronal differentiation, and ALK knockout resulted in hypogonadotropic hypogonadism in male mice due to reduction in Gonadotropin-releasing hormone (GnRH)-positive neurons." (PMID 32059449, 2020). "Taken together, the data presented here suggests that ALK plays a potential role in hypogonadotropic hypogonadism in males." (PMID 25955180, 2015). "Taken together, examination of hypothalamic GnRH levels by both convention confocal microscopy and OPT analysis indicates a role for ALK in the modulation of the hypothalamic-pituitary-gonadal axis affecting hypogonadotropic hypogonadism." (PMID 25955180, 2015). "This decrease in serum testosterone levels in ALK mutant males at P40 supports our observation that ALK mutant mice exhibit hypogonadotropic hypogonadism as compared to their wild type littermates." (PMID 25955180, 2015). "Thus, ALK appears to be involved in hypogonadotropic hypogonadism by regulating the timing of pubertal onset and testis function at the upper levels of the hypothalamic-pituitary gonadal axis." (PMID 25955180, 2015). "Thus our mouse ALK knockout model displays hypogonadotropic hypogonadism." (PMID 25955180, 2015).
IgG4-related disease (2 papers, 2023 to 2025). "All 56 IgG4-related disease subjects were negative for ALK and ROS1 on immunohistochemical analysis; 6 subjects were negative on the fusion assay." (PMID 37685395, 2023). "The lesion was negative for ALK, IgG4, and other tumor-specific markers, ruling out IMT and IgG4-related disease." (PMID 40964556, 2025).
infiltrating ductal carcinoma (2 papers, 2009 to 2015). "However, ALK overexpression as high as 75 % in infiltrating ductal carcinoma has been reported in a small cohort representing 63 samples from 22 patients." (PMID 26384210, 2015). "In conclusion, we describe a case of primary ALK negative ALCL arising in the site of saline filled left breast implant 12 years after the patient underwent modified radical mastectomy followed by adjuvant chemotherapy for infiltrating ductal carcinoma of the breast." (PMID 19341480, 2009).
influenza (2 papers, 2016 to 2026). An acute viral infection of the respiratory tract, occurring in isolated cases, in epidemics, or in pandemics; it is caused by serologically different strains of viruses (influenzaviruses) designated A, B, and C, has a 3-day incubation period, and usually lasts for 3 to 10 days. "Our results revealed that CB, epigoitrin, PEP, or PEP + ALK + OA demonstrated their anti-influenza activities by therapeutic action, prophylaxis of cells, and inhibition of virus attachment." (PMID 26989425, 2016). "The results revealed that CB, epigoitrin, PEP, and PEP + ALK + OA exert their anti-influenza activity via inhibiting the virus multiplication, prophylaxis, and blocking the virus attachment." (PMID 26989425, 2016). "Importantly, the repurposed ALK-inhibitors crizotinib, brigatinib, and ceritinib also gave some protection in mice against lethal viral challenges with influenza and SARS-CoV-2, respectively." (PMID 42263913, 2026). "The objective of the present study was to elucidate the possible anti-influenza mechanisms of CB and epigoitrin and compare with the phenylpropanoids portion and the mixture of phenylpropanoids, alkaloids, and organic acid portions (PEP + ALK + OA)." (PMID 26989425, 2016).
juvenile myelomonocytic leukemia (2 papers, 2019 to 2022). A myelodysplastic/myeloproliferative neoplasm of childhood that is characterized by proliferation principally of the granulocytic and monocytic lineages. "In a genomic study of patients with juvenile myelomonocytic leukemia (JMML), 16 patients had no RAS variants, and in three of these that were 56 months of age or older, the researchers identified ALK/ROS1 tyrosine kinase fusions (DCTN1-ALK, RANBP2-ALK, and TBL1XR1-ROS1)." (PMID 36295546, 2022).
lactic acidosis (2 papers, 2023 to 2026). Metabolic acidosis characterized by the accumulation of lactate in the body. "We, herein, report a rare case of the common type of ALK‐positive ALCL complicated by lactic acidosis." (PMID 36794043, 2023).
Lymphomatoid Papulosis (2 papers, 2021 to 2025). A chronic, recurrent cutaneous disorder characterized by the presence of spontaneously regressing papules. "The WHO classification distinguishes ALK‐positive ALCL, ALK‐negative ALCL, breast implant‐associated ALCL and cutaneous CD30‐positive lymphoproliferations (cutaneous ALCL and lymphomatoid papulosis)." (PMID 40351161, 2025).
mastocytosis (2 papers, 2010 to 2014). A clonal myeloproliferative neoplasm characterized by the proliferation and accumulation of neoplastic mast cells in one or multiple organs or organ systems. "In this regard, it is also noteworthy that neoplastic MC in human mastocytosis did not express ALK." (PMID 21297223, 2010). "However, human neoplastic MC in SM did not express ALK, and similar to IL-9, NPM-ALK alone led to MC hyperplasia only, but did not lead to the clinical picture of overt mastocytosis." (PMID 21297223, 2010). "So far, however, the ALK tyrosine kinase and NPM have not been analyzed in the context of mastocytosis." (PMID 21297223, 2010).
metanephric adenoma (2 papers, 2019 to 2024). A benign, well-circumscribed renal cortical neoplasm affecting females more often than males. "Additionally, ALK::STRN and ALK::PLEKHA7 gene fusions have been described in tumors mimicking metanephric adenoma, corroborating the notion that gene fusion partners might impact morphology and even clinical outcomes." (PMID 37999735, 2024).